CFAP57 (cilia and flagella associated protein 57)
Description:
Associates with components of the nexin-dynein regulatory complex (N-DRC), a key regulator of ciliary/flagellar motility, and might act as an inner dynein arm (IDA) hub or linkage.
Synonyms: WDR65; FLJ32000; SPGF95; VWS2
Tractability: Small molecule: a structure with a bound ligand is known. PROTAC: ubiquitination databases record sites on it.
Gene: Protein-coding gene on chromosome 1 (43,172,330 to 43,254,358, forward strand). Ensembl gene ENSG00000243710.
Subcellular location: Cytoplasm, cytoskeleton, cilium axoneme
Subcellular location (Human Protein Atlas): Cytosol; Primary cilium
Gene Ontology:
Cellular component: cilium; axoneme; sperm flagellum
Genetic constraint (gnomAD): Loss-of-function variants: 110 observed, 140.03 expected, observed/expected ratio (o/e) 0.79, 90% interval 0.67 to 0.92. The upper end of that interval is the gene's LOEUF score, 0.92, which puts it in group 3 of 6, group 1 being the genes least tolerant of losing a copy. Missense variants: 1,315 observed, 1,510.9 expected, observed/expected ratio (o/e) 0.87, 90% interval 0.83 to 0.91. Synonymous variants: 496 observed, 550.98 expected, observed/expected ratio (o/e) 0.9, 90% interval 0.84 to 0.97.
Gene-disease validity (ClinGen):
ClinGen rates the evidence that CFAP57 causes each of these diseases.
primary ciliary dyskinesia (autosomal recessive): Limited. A rare, genetically heterogeneous, primarily respiratory disorder characterized by chronic upper and lower respiratory tract disease.
Homologues: Orthologues: chimpanzee CFAP57 (99% identical), macaque CFAP57 (98% identical), rabbit CFAP57 (91% identical), guinea pig CFAP57 (89% identical), rat Cfap57 (88% identical), mouse Cfap57 (88% identical), pig CFAP57 (79% identical), tropical clawed frog cfap57 (67% identical), zebrafish cfap57 (42% identical), Drosophila melanogaster tous (24% identical).
Diseases named in the same sentence as CFAP57 in open-access papers:
CFAP57 is named in the same sentence as 8 diseases in open-access papers, as found by Europe PMC text mining. Sharing a sentence is not in itself a finding about the gene and the disease. The quoted sentences say what the papers report.
infertile (2 papers, 2023 to 2025). "Here, we report novel biallelic mutations in the CFAP57 gene identified in two infertile males from two unrelated families." (PMID 41466333, 2025). "Hence, Cfap57M/M mice recapitulated the MMAF phenotype found in the affected individuals carrying homozygous M1 mutations, showing that the CFAP57 mutation is indeed pathogenic for MMAF in both infertile cases and mutant mice." (PMID 36752199, 2023). "In this study, we identified novel CFAP57 gene mutations in two unrelated infertile males: the first patient (P1) carrying a homozygous nonsense mutation [NM_001378189.1: exon 20: c.3250 C >T (p.R1084X), NM_001195831.3:exon 21:c." (PMID 41466333, 2025). "CRISPR-Cas9-generated CFAP57 mutant mice recapitulated human MMAF phenotypes, exhibiting structural flagellar defects and complete infertility." (PMID 41466333, 2025).
male infertility (2 papers, 2023 to 2025). The inability of the male to effect fertilization of an ovum after a specified period of unprotected intercourse. "Collectively, these findings demonstrate that loss-of-function mutations in CFAP57 caused MMAF and male infertility in mice and humans, providing evidence for an essential and specific role for long transcript-encoded CFAP57 in male reproduction." (PMID 36752199, 2023). "Therefore, our findings provide novel insights into the molecular basis of sperm flagellogenesis and offer a valuable treatment option for CFAP57-associated male infertility." (PMID 41466333, 2025). "Furthermore, we demonstrated that ICSI is an effective method to rescue CFAP57-associated male infertility." (PMID 41466333, 2025). "Fortunately, ICSI can overcome CFAP57-associated male infertility." (PMID 41466333, 2025). "Here, we found three novel mutations [c.3250 C >T (p.R1084X), c.1340T >C (p.V447A), c.1856G >A (p.R619H)] in CFAP57 from male infertility in Chinese patients." (PMID 41466333, 2025). "Altogether, these results indicate that deletion of Cfap57 impairs spermatogenesis, resulting in male infertility." (PMID 41466333, 2025). "Future studies addressing these limitations, particularly the acquisition of additional patient samples and isoform-specific functional analyses, would further strengthen our understanding of CFAP57’s role in male infertility." (PMID 41466333, 2025). "In conclusion, our study based on MMAF-affected individuals and the corresponding mutant mouse models demonstrates that homozygous loss-of-function mutations in CFAP57 cause MMAF and male infertility in mice and humans due to the disruption of IDA assembly." (PMID 36752199, 2023). "Together, our findings establish CFAP57 as an important mediator of sperm flagellogenesis that orchestrates MYH10 and IFT88 positioning and intraflagellar transport dynamics to maintain flagellar integrity, providing molecular insights into MMAF-associated male infertility." (PMID 41466333, 2025). "CFAP57 can be used as a genetic screening marker in genetic counseling and diagnosis of MMAF and male infertility." (PMID 36752199, 2023). "Collectively, these findings not only clarify the role of CFAP57 in MMAF pathogenesis but also reveal a previously unrecognized function of MYH10 in sperm flagellogenesis, providing new insights into the molecular etiology of male infertility and highlighting potential therapeutic targets." (PMID 41466333, 2025).
primary ciliary dyskinesia (2 papers, 2020 to 2025). "It has been reported that the loss of CFAP57 would cause primary ciliary dyskinesia." (PMID 41466333, 2025).
influenza (1 paper, 2025). An acute viral infection of the respiratory tract, occurring in isolated cases, in epidemics, or in pandemics; it is caused by serologically different strains of viruses (influenzaviruses) designated A, B, and C, has a 3-day incubation period, and usually lasts for 3 to 10 days. "Finally, through transcriptome analysis, we identified several genes that may be involved in the anti-influenza effects of A2CA, including TP53TG3C, CFAP57 and SNX30-DT." (PMID 40431640, 2025).
CFAP57 also shares sentences with these, for which no sentence is quoted: bronchiectasis (1 paper); otitis media (1); Respiratory distress (1); sinusitis (1).